C1GALT1 (core 1 synthase, glycoprotein-N-acetylgalactosamine 3-beta-galactosyltransferase 1)
Diseases named in the same sentence as C1GALT1 in open-access papers (continued):
Sharing a sentence is not in itself a finding about the gene and the disease.
Thrombocytopenia (1 paper, 2017). A reduction in the number of circulating thrombocytes. "Mice deficient in C1GALT1 protein develop thrombocytopenia and kidney disease attributed to defective O-glycosylation of cell-surface proteins." (PMID 28187132, 2017).
thyroid adenocarcinoma (1 paper, 2024). "In this study, we discovered that the expression level of C1GALT1 was significantly increased in thyroid adenocarcinoma tissues and cell lines (p < 0.01)." (PMID 38845937, 2024).
tumor (40 papers, 2014 to 2025). "The second cohort included 63 OS patients with TNM staging and clinical stage data (OS208a), which allowed us to analyze the association between C1GALT1 expression and tumor grade." (PMID 39844613, 2025). "Our investigation is distinguished by its in‐depth analysis across a local NTUH cohort and two OS tissue array cohorts, revealing significant C1GALT1 overexpression in advanced‐stage OS, associated with poor survival, and tumor recurrence." (PMID 39844613, 2025). "Previously, C1GALT1 upregulation was associated with tumor progression and metastasis in breast, prostate, lung, liver, bladder, pancreas, stomach, and colon cancers." (PMID 40548474, 2025). "Overexpression of C1GalT1 is consistently reported to be associated with tumour malignancy, poor prognosis and poor patients’ survival." (PMID 37612278, 2023). "In this study, interaction of M1 macrophages with C1GalT1-suppressed tumour cells is associated not only with higher tumour cell engulfing but also with lower macrophage secretion of IL-6 in comparison to their interaction with higher C1GalT1-expressing cells." (PMID 37612278, 2023). "In contrast, the up-regulation of C1GALT1 is also observed in various cancers and is associated with poor survival and tumor progression." (PMID 35207462, 2022). "C1GALT1 high expression was significantly associated with differentiated tumor histology (p < 0.001)." (PMID 35169131, 2022). "Our data showed that C1GALT1 expression was significantly associated with differentiated tumor histology, correlated with TrkA expression, and predicted good prognosis independently in NB." (PMID 35169131, 2022). "C1GalT1, an enzyme participating in the elongation of Tn structure, is often overexpressed in tumours, causing accumulation of T antigens." (PMID 34681197, 2021). "Silencing or loss of C1GALT1 inhibited cell viability, migration, invasion, tumor growth and metastasis, as well as increased apoptosis and cytotoxicity of 5-fluorouracil in AGS and MKN45 cells." (PMID 32005975, 2020). "In SAS cells, C1GALT1-mediated tumor growth was partially reversed by itraconazole, which is closely associated with partially decreased C1GALT1 protein levels in tumors." (PMID 29930379, 2018). "However, these correlations remain associative, and further, in vitro and in vivo, functional studies are required to establish causality and define the mechanistic underpinnings of C1GALT1's role in cell cycle regulation, tumor growth, and metastasis." (PMID 40548474, 2025). "In a syngeneic mouse model, we found that the loss of C1GALT1 in HNC cells suppressed tumor growth." (PMID 37452653, 2024). "Interaction of M1 macrophages with C1GalT1 knockdown SW620shC1GT and HCT116F3shC1GT cancer cells was found to be associated with 62%% and 78%, respectively, higher macrophage-tumour cell phagocytotic events in comparison to interaction with SW620shCon and HCT116F3shCon cells." (PMID 37612278, 2023). "Interestingly, the results of our study revealed that TrkA expression was positively correlated with C1GALT1 (p = 0.001) in NB tumors, and C1GALT1 high expression was significantly associated with differentiated tumor histology." (PMID 35169131, 2022). "In a mouse model, C1GALT1 loss reduced tumor burden in HNSCC." (PMID 32075174, 2020). "The results also showed that the loss of C1GALT1 inhibited tumor sizes and tumor growth." (PMID 32005975, 2020). "While, presumably, loss of C1GalT1 should favor formation of truncated glycans and tumor progression, loss of Core 1 glycans may favor formation of Core 3 or 4 structures that correlate with less aggressive tumors." (PMID 27483328, 2016). "Disruption in Cosmc expression or function has been shown to lead to misfolded or inactive C1GALT1 protein, resulting in the expression of truncated glycan structures such as the Tn antigen, which is frequently observed in various cancers and is associated with tumor progression and immune evasion." (PMID 40548474, 2025).
tumor (continued). "Having shown that change of C1GalT1 expression alters tumour cell interaction with macrophages, mediated by MGL in vitro, we then investigated whether change of C1GalT expression is associated with change of macrophage activity in the tumour microenvironment in a mouse model in vivo." (PMID 37612278, 2023). "Emerging evidence suggests that C1GalT1 fulfills a dual role in cancer, acting in both tumor promotion and suppression." (PMID 40548474, 2025). "To prepare to test this approach in vivo, we first examined the impact of C1GALT1 KO and itraconazole treatment on Capan-2 tumor growth." (PMID 41372740, 2025). "Collectively, these results underscore the critical role of C1GALT1 in cancer progression across multiple tumor types and its potential as a target for therapeutic intervention." (PMID 40548474, 2025). "Median C1GalT1 gene expression differences between normal and tumor samples across different cancer types." (PMID 40548474, 2025). "Our findings indicated that C1GALT1 significantly enhanced drug resistance and tumor growth in OS cells, primarily through the ABCC1 pathway." (PMID 39844613, 2025). "The expression levels of the C1GalT1 gene in tumor and normal tissue were compared in log2 fold change using the Xena web portal and the TCGA cancer datasets." (PMID 40548474, 2025). "C1GalT1 modulates O‐glycosylation of the epidermal growth factor receptor, enhancing ligand‐binding affinity and downstream signaling, which promotes tumor progression." (PMID 40548474, 2025). "Our results are applicable to other oncogenic ES fusion-proteins driven by EWSR1, as genetic or pharmacological inhibition of C1GALT1 also decreases cell viability and tumor growth of ES cells that harbor an EWSR1::ERG fusion." (PMID 39894896, 2025). "Previous studies have reported that altered glycosylation patterns, including truncated O‐glycans generated by aberrant C1GALT1 activity, can influence tumor progression, invasion, and immune evasion." (PMID 40548474, 2025). "Median C1GalT1 DNA methylation level differences between normal and tumor samples across different cancer types." (PMID 40548474, 2025). "Tumor tissues in stomach, pancreatic, colorectal, lung, bladder, and endometrioid cancers exhibited significantly higher median C1GalT1 expression than healthy tissues." (PMID 40548474, 2025). "By day 28, tumor volume analyzed by calipers indicated a 46% increase in the C1GALT1 overexpression group compared to the control group, while ABCC1 knockdown reduced tumor growth by 38%, aligning with the reduction observed in the IVIS analysis." (PMID 39844613, 2025). "In NSG mice, HPA-directed CAR-T cells significantly reduced tumor size in Capan-2 C1GALT1 KO tumors." (PMID 41372740, 2025). "Average DNA methylation levels of the C1GalT1 gene were analyzed between tumor and normal tissues using beta values from the Xena web portal and TCGA datasets." (PMID 40548474, 2025). "The study assessed the correlation between the C1GALT1 gene expression and the abundance of tumor‐infiltrating immunosuppressive Tregs and MDSCs across multiple cancer types." (PMID 40548474, 2025). "The results demonstrated that C1GALT1 knockdown reduced tumor nodules in the tibia region, consistent with tumor volume analysis." (PMID 39844613, 2025). "The reported studies state that the key player or core player of O-glycan’s C1GALT1 plays an important role in tumor progression in lungs through the phenotypic change induction of the EMT signaling pathway." (PMID 41451346, 2025). "The studies showed that C1GalT1 expression in tumor cells plays a dual role in modulating both tumor cell–cell interactions and tumor–macrophage communication through galectin‐3 and MGL, collectively influencing cancer development and progression." (PMID 40548474, 2025). "The correlation between C1GALT1 gene expression and tumor metastasis‐related genes in various cancer types." (PMID 40548474, 2025).
tumor (continued). "Increased CTL‐induced apoptosis was noted in C1galt1 knockout tumor cells compared with that in the Mock cells." (PMID 37452653, 2024). "Some studies have reported that the loss of C1GALT1 function can promote malignant properties in certain cancers, implying a tumor suppressive role of C1GALT1." (PMID 37452653, 2024). "Here, we evaluated the role of C1GALT1‐mediated O‐glycosylation in the crosstalk between tumor cells and immune cells." (PMID 37452653, 2024). "Core 1 β 1,3-galactosyltransferase 1 (C1GALT1) acts as an important glycosyltransferase in the occurrence and development of tumor glycosylation." (PMID 38845937, 2024). "Overall, O‐glycan truncation by C1GALT1 knockout in tumor cells skewed the macrophages and CTLs toward antitumorigenic phenotypes." (PMID 37452653, 2024). "Consistent with the effect of C1galt1 knockout, the BMDMs cocultured with itraconazole‐treated tumor cells were also M1 polarized." (PMID 37452653, 2024). "The results of this analysis consistently demonstrated significantly elevated expressions of C1GALT1 protein within LUAD tissues when compared with that in adjacent non-tumor tissues." (PMID 38662050, 2024). "In a previous study, we observed that C1GALT1 regulates ligand‐binding and phosphorylation of EGFR and enhances metastasis of HNC tumors, indicating the tumor‐promoting role of C1GALT1 in HNC." (PMID 37452653, 2024). "C1GALT1‐mediated O‐glycosylation is one of the glycocodes used by cancer cells to establish an immuno‐privileged environment that favors tumor progression." (PMID 37452653, 2024). "Aberrant glycosylation has an effect on tumor progression and chemoresistance in a variety of cancers, and C1GALT1 is the key enzyme to control GalNAc-type O-glycosylation." (PMID 38807485, 2024). "The expression of C1GALT1 was significantly higher in LUAD tissues than in adjacent non-tumor tissues both at mRNA and protein level." (PMID 38662050, 2024). "In the current study, 2 primary public databases (TCGA and GEO) were utilized in addition to clinical samples (98 tumor tissues) to investigate the clinical significance of C1GALT1." (PMID 38662050, 2024). "In this study, we demonstrated that, being a crucial enzyme for O‐glycan elongation, C1GALT1 not only directly promotes cell survival and invasion but also facilitates tumor‐mediated immune evasion." (PMID 37452653, 2024). "Our study showed that C1GALT1 inhibitor itraconazole suppressed tumor growth and introduced tumor‐reactive T cells into the TME." (PMID 37452653, 2024). "Here, we demonstrated that C1GALT1‐mediated O‐glycosylation contributes to the tumor‐induced immune tolerance by influencing the composition of tumor secretomes." (PMID 37452653, 2024). "The variation in the C1GALT1-mediated tumor microenvironment and signaling pathways requires further exploration." (PMID 38845937, 2024). "Consistent with culture findings, the knockdown of C1GALT1 by doxycycline treatment significantly reduced the tumor growth rate compared to mice inoculated with the control cell line." (PMID 38622340, 2024). "This suggests that macrophages, in particular M1 type macrophages, secret significantly higher amounts of cytokines when they interact with C1GalT1-expressing tumour cells than with C1GalT1-suppressed tumour cells." (PMID 37612278, 2023). "Together, these results suggest a critical role of higher C1GalT1 expression by tumour cells on tumour cell avoidance of immune surveillance mediated by macrophages." (PMID 37612278, 2023). "Tumours in ME C1galt1-/-/Erb mice was shown to attract more MGL-expressing macrophages/dendritic cells in the tumour microenvironment than tumours in C1galt1f/f /Erb mice." (PMID 37612278, 2023). "This notion is supported by the discovery that more macrophages were seen in the tumour microenvironment of the ME C1galt1-/- /Erb mice than in the C1galt1f/f/Erb mice." (PMID 37612278, 2023).
tumor (continued). "These suggest that change of C1GalT1 expression in tumour cells can substantially alter tumour cell interaction with galectin-3 and MGL." (PMID 37612278, 2023). "The alteration of binding of these cell membrane proteins by MGL in response to change of C1GalT1 in tumour cells suggests possible involvement of these cell surface glycoproteins in MGL-mediated immune modulation in cancer." (PMID 37612278, 2023). "Higher expression of C1GalT1 by tumour cells would therefore lead to less anti-tumour M1 type macrophages to be attracted to the tumour microenvironment for M1- macrophage-mediated anti-tumour immune reactions." (PMID 37612278, 2023). "Further research using macrophages from healthy people will help to provide more insight into C1GalT1-medaited regulation of cancer-macrophage interactions in the tumour microenvironment." (PMID 37612278, 2023). "The presence of a large number of DCs and macrophages in the tumour surroundings of ME C1galt1-/-/Erb mice compared with C1galt1f/f/Erb mice is in support of this high possibility." (PMID 37612278, 2023). "Crucially, C1GalT1 suppression significantly reduced galectin-3-mediated tumour cell-cell interaction and galectin-3-promoted tumour cell activities." (PMID 37612278, 2023). "This suggests change of C1GalT1 expression by tumour cells also influences M2-mediated immune reactions in TME." (PMID 37612278, 2023). "The demonstration of significantly lower viability of C1GalT1-suppressed tumour cells in comparison with the control cells after interaction with M1 macrophages also supports this notion." (PMID 37612278, 2023). "Having shown that C1GalT1 suppression in tumour cells increases tumour cell interaction with macrophages, we then assessed the influence of such interaction on macrophage activities." (PMID 37612278, 2023). "A higher level of MGL expression was observed within tumours as well as in the tumour surroundings in ME C1galt1-/-/Erb mice (12.7 ± 4.3% staining) than in C1galt1f/f/Erb mice (3.2 ± 0.5%)." (PMID 37612278, 2023). "More MGL-expressing macrophages and dendritic cells were seen to be attracted to the tumour microenvironment in ME C1galt1-/-/Erb mice than in C1galt1f/f /Erb mice." (PMID 37612278, 2023). "C1GalT1-expressing cancer cells implanted in chick embryos resulted in the formation of significantly bigger tumours than C1GalT1-suppressed cells and the presence of galectin-3 increased tumour growth of C1GalT1-expressing but not C1GalT1-suppressed cells." (PMID 37612278, 2023). "Having shown that suppression of C1GalT1 increases MGL binding to tumour cells, we then investigated the influence of C1GalT1 alteration on tumour cell interaction with macrophages differentiated from THP-1 monocytes." (PMID 37612278, 2023). "Among the identified hub genes, we found that only C1GALT1 was significantly overexpressed in the tumor cells, whereas LEP4, ERG, and FLT1 were primarily expressed in the endothelial cells in scRNA-seq dataset." (PMID 37735483, 2023). "It is very possible that the altered tumour cell interaction with macrophages mediated by MGL as a result of C1GalT1 suppression shown in this study also occurs to MGL-mediated DC-tumour cell interaction and in DC-mediated immune reactions." (PMID 37612278, 2023). "A modest elevation of IL-10 secretion was seen in this study from macrophage interaction with C1GalT1-expressing tumour cells than with C1GalT1 suppressed cells." (PMID 37612278, 2023). "One of the exciting discoveries in this study is the revelation that suppression of C1GalT1 expression reduces the tumour cell interaction mediated by galectin-3 but reciprocally increases their interaction with macrophages mediated by MGL." (PMID 37612278, 2023). "Together, these results indicate that lower C1GalT1 expression by tumour cells lead to greater interaction of the tumour cells with macrophages and this interaction is largely mediated by MGL." (PMID 37612278, 2023).